PPP1R3A (protein phosphatase 1 regulatory subunit 3A)
Description:
Seems to act as a glycogen-targeting subunit for PP1. PP1 is essential for cell division, and participates in the regulation of glycogen metabolism, muscle contractility and protein synthesis. Plays an important role in glycogen synthesis but is not essential for insulin activation of glycogen synthase (By similarity).
Synonyms: PP1G; GM; PPP1R3
Tractability: Antibody: UniProt predicts a signal peptide or a membrane-spanning region.
Gene: Protein-coding gene on chromosome 7 (113,876,777 to 114,075,920, reverse strand). Ensembl gene ENSG00000154415.
Subcellular location: Membrane
Gene Ontology:
Molecular function: glycogen binding; protein phosphatase 1 binding
Biological process: regulation of glycogen biosynthetic process
Cellular component: protein phosphatase type 1 complex; membrane
Genetic constraint (gnomAD): Loss-of-function variants: 24 observed, 39.24 expected, observed/expected ratio (o/e) 0.61, 90% interval 0.44 to 0.86. The upper end of that interval is the gene's LOEUF score, 0.86, which puts it in group 3 of 6, group 1 being the genes least tolerant of losing a copy. Missense variants: 1,331 observed, 1,337.2 expected, observed/expected ratio (o/e) 1, 90% interval 0.95 to 1.04. Synonymous variants: 479 observed, 468.77 expected, observed/expected ratio (o/e) 1.02, 90% interval 0.95 to 1.1.
Homologues: Orthologues: chimpanzee PPP1R3A (99% identical), macaque PPP1R3A (92% identical), dog PPP1R3A (77% identical), pig PPP1R3A (74% identical), rabbit PPP1R3A (72% identical), guinea pig PPP1R3A (66% identical), rat Ppp1r3a (64% identical), mouse Ppp1r3a (62% identical), tropical clawed frog ppp1r3a (26% identical), zebrafish ppp1r3aa (18% identical), zebrafish ppp1r3ab (17% identical), Drosophila melanogaster Gbs-70E (6% identical), and 1 more. Paralogues in human: PPP1R3F (14% identical), PPP1R3B (7% identical), PPP1R3D (7% identical), PPP1R3C (6% identical), PPP1R3G (6% identical), PPP1R3E (6% identical).
Diseases named in the same sentence as PPP1R3A in open-access papers:
PPP1R3A is named in the same sentence as 101 diseases in open-access papers, as found by Europe PMC text mining. Sharing a sentence is not in itself a finding about the gene and the disease. The quoted sentences say what the papers report.
Insulin resistance (15 papers, 2006 to 2024). Increased resistance towards insulin, that is, diminished effectiveness of insulin in reducing blood glucose levels. "We originally identified the PPP1R3A FS mutation in a large kindred with severe insulin resistance and type 2 diabetes." (PMID 18232732, 2008). "In 2002 a digenic form of severe insulin resistance was reported: in a human pedigree, the patients carried both a stop/frameshift mutation in the regulatory subunit of PPP1R3A as well as a mutation in the gene encoding for the transcription factor PPAR." (PMID 18232730, 2008). "In agreement with our study, in Maya population the rs1799999 polymorphism of the PPP1R3A gene is associated with T2D (OR = 1.625, p = 0.014); interestingly, the carriers of the polymorphism presented insulin resistance." (PMID 37291636, 2023). "Indeed, gene variants of PPP1R3A, the gene encoding GM, have been reported to cause impaired glycogen synthesis and muscle glycogen content resulting in insulin resistance and type 2 diabetes in human patients." (PMID 24244723, 2013). "In that pedigree, severe insulin resistance was restricted to individuals who were doubly heterozygous for the PPP1R3A FS variant and an unlinked loss-of-function mutation in PPARG (AAA553T; stop codon 186), which encodes a key transcriptional regulator of adipocyte differentiation." (PMID 18232732, 2008). "Taken together, these data suggest that carriers of the PPP1R3A FS variant may be predisposed to develop severe insulin resistance in the setting of adipose tissue dysfunction." (PMID 18232732, 2008). "The differential effect on peripheral insulin resistance between men and women appears to be associated with the SLC16A11 and PPP1R3A genes, since the effect size of the SNPs of these genes was much larger in women." (PMID 37291636, 2023). "The KEGG pathway analysis indicated that the upregulated DEGs were significantly enriched in insulin resistance, which included PPP1R3A and PPP1R3C." (PMID 35499169, 2022). "In a second family, weight gain appeared to induce disproportionate insulin resistance in PPP1R3A FS carriers." (PMID 18232732, 2008). "Previous study indicated that disruption of PPP1R3A promoted the development of insulin resistance." (PMID 35499169, 2022). "Second, impaired glycogen synthesis in muscle does not a priori lead to insulin resistance, impaired glucose tolerance, or diabetes, since glucose tolerance was normal in carriers of mutations in both the PPP1R3A and GYS1 genes." (PMID 18232730, 2008). "Besides, Lingguizhugan Decoction improved insulin resistance in overweight/obese patients with MASLD by increasing the levels of DNA N6-methyladenine modification of protein phosphatase 1 regulatory subunit 3A (PPP1R3A) and autophagy related 3 (ATG3)." (PMID 39440040, 2024). "In addition, several energy metabolic processes, such as the PI3K-Akt pathway (EPHA2, FLT4, ITGA5, and LPAR6), cholesterol metabolism (APOE and CD36), and insulin resistance (FOLR1, CALM14, and PPP1R3A), were enriched in ApoE4 mice." (PMID 36720919, 2023).
type 2 diabetes (13 papers, 2008 to 2026). "It is therefore suggested that dysfunction of the protein coded by PPP1R3A may contribute to the pathophysiology of human type 2 diabetes." (PMID 32670085, 2020). "The PPP1R3A FS variant is not captured by existing fixed single nucleotide polymorphism arrays, so one cannot infer anything about its impact on diabetes risk from the recently reported type 2 diabetes genomewide association studies." (PMID 18232732, 2008). "The copy numbers of studies for risky genes in type-2 diabetes patients have shown that epidermal growth factor receptor (EGFR), E2F transcription factor 1 (E2F1), protein phosphatase 1 regulatory subunit 3A (PPP1R3A), human leukocyte antigen (HLA), and tetraspanin 8 (TSPAN8) are important." (PMID 34563047, 2021). "Baseline muscle glycogen concentration (23.9 ± 14.7 mmol/l) was significantly lower (65%, p = 0.002) in PPP1R3A FS heterozygotes than in nondiabetic volunteers (68.9 ± 4.1 mmol/l) and even volunteers with type 2 diabetes (57.1 ± 3.6 mmol/l, p = 0.01)." (PMID 18232732, 2008).
diabetes (7 papers, 2008 to 2023). "More genes are shared between pairs of phenotypes: NPP1, AKT2 between diabetes and obesity, HNF1A, INSR and PPP1R3A between ovarian cysts and diabetes, and PTEN between ovarian cysts and obesity." (PMID 31307376, 2019). "In our study, the rs151310594 identified in the PPP1R3A gene was absent in the diabetic mother, thus ruling out the possibility of its role in the development of diabetes in this family." (PMID 38162681, 2023). "We genotyped 744 adults without diabetes from an Oxfordshire Biobank and found that the PPP1R3A FS allelic frequency was 1.46%." (PMID 18232732, 2008).
heart failure (2 papers, 2018 to 2019). Inability of the heart to pump blood at an adequate rate to meet tissue metabolic requirements. "Here, the authors present a high-fidelity tissue collection from rapidly preserved failing and non-failing control hearts which are used for eQTL mapping and network analysis, resulting in the prioritization of PPP1R3A as a heart failure gene." (PMID 31235787, 2019). "We present a global gene interaction map of the human heart failure transition, identify previously unreported cardiac eQTLs, and demonstrate the discovery potential of disease-specific networks through the description of PPP1R3A as a central regulator in heart failure." (PMID 31235787, 2019).
Arrhythmia (1 paper, 2025). Any cardiac rhythm other than the normal sinus rhythm. "The E3 ubiquitin ligase WWP2 and the protein phosphatase 1 regulatory subunit PPP1R3A exhibit a dynamic and inverse regulatory relationship during the progression of arrhythmia‐induced cardiac damage." (PMID 41362701, 2025). "In a murine model of arrhythmia, PPP1R3A is significantly overexpressed during the initial stages, a period when WWP2 is only marginally upregulated." (PMID 41362701, 2025).
atrial fibrillation (1 paper, 2021). A disorder characterized by an electrocardiographic finding of a supraventricular arrhythmia characterized by the replacement of consistent P waves by rapid oscillations or fibrillatory waves that vary in size, shape and timing and are accompanied by an irregular ventricular response. "Reducing the concentration of PP1 at the SR by ablating its targeting subunit PPP1R3A has been shown to lead to atrial fibrillation, which is consistent with a smaller bistable region expected from reducing [PP1] in our model." (PMID 34320358, 2021).
cardiomyopathy (1 paper, 2019). A disease of the heart muscle or myocardium proper. "Elimination of PPP1R3A in a murine model of cardiomyopathy revealed a maladaptive role for this gene in HF, and our in vitro studies highlight the metabolic switch of failing myocardium: toward inefficient glycolytic glucose metabolism and away from the use of pyruvate in respiratory metabolism." (PMID 31235787, 2019).
diabetic nephropathy (1 paper, 2023). "PPP1R3A gene is associated with T2DM and plays a crucial role in glycogen synthesis in the tubules of the kidney, leading to diabetic nephropathy." (PMID 37033211, 2023). "The genes that contributed to the biological relevance of diabetic nephropathy, include gene TTN (rs72646845), PI16 (rs113848006), DPY6 (rs36027551), CROCC (rs41272737), PPP1R3A (rs1799999), ZNF136 (rs140861589), HSPA12B (rs6076550), and FRMD4A (rs1541010)." (PMID 37033211, 2023).
liposarcoma (1 paper, 2018). A usually painless malignant tumor that arises from adipose tissue. "In our study we also noted deleterious mutations in 7 other genes (CTNNB1 (R151H), MECOM (R208C), ZNF536 (T688M), EML4 (W729L), CSMD3 (P627S), PBRM1 (N639K), PPP1R3A (C788Y)) that have also not been described previously in WD/DD liposarcoma." (PMID 29731991, 2018).
partial lipodystrophy (1 paper, 2018). Loss and redistribution of subcutaneous and/or visceral adipose tissue from specific regions of the body. "The physiological consequences of a PPP1R3A gene variant, identified in relation to digenic inheritance of partial lipodystrophy, was tested using the RbG concept." (PMID 29040543, 2018).
PPP1R3A also shares sentences with these, for which no sentence is quoted: infection (30 papers); cancer (14); tumor (14); depression (10); Cognitive impairment (7); virus infection (7); HCMV infection (5); ischemia (5); colitis (4); Stroke (4); Alzheimer disease (3); cardiovascular disease (3); liver fibrosis (3); memory impairment (3); neurologic disease (3); osteoporosis (3); Sepsis (3); Anxiety (2); Arthritis (2); cardiac ischemia (2); cerebral infarction (2); Cerebral ischemia (2); colorectal cancer (2); dementia (2); energy metabolism disorder (2); glioma (2); Hepatic steatosis (2); Hypertension (2); latent infection (2); myocardial infarction (2).
A further 61 diseases each share a sentence with PPP1R3A in 2 papers or fewer.